TGFBI (transforming growth factor beta induced)
Diseases named in the same sentence as TGFBI in open-access papers (continued):
Sharing a sentence is not in itself a finding about the gene and the disease.
corneal dystrophies (continued). "Corneal dystrophies caused by mutations in TGFBI are characterized by abnormal extracellular deposits of mutated TGFBI protein in the corneal stroma." (PMID 20360992, 2010). "Among those mutations reported, R124 appeared to be a “hot-spot” point mutation in TGFBI as the R124 mutation has been detected in three types of corneal dystrophies, including Avellino corneal dystrophy, lattice corneal dystrophy type I, and RBCD." (PMID 20360992, 2010). "To date, more than 30 mutations in TGFBI have been reported to cause dominantly inherited corneal disorders, although homozygous mutations are also reported in severe forms of corneal dystrophy patients." (PMID 20161820, 2010). "There is a strong correlation between phenotype-genotype in most corneal dystrophies caused by TGFBI mutations." (PMID 20360992, 2010). "Currently, more than 30 mutations in TGFBI have been demonstrated in four different types of corneal dystrophies." (PMID 20360992, 2010). "Our findings extend the mutational spectrum of TFGBI, and this is also the first extensively delineated TGFBI mutation profile associated with the various corneal dystrophies in the Chinese population." (PMID 20664689, 2010). "We now describe the first cases of corneal dystrophy associated with both R124H and N544S mutations of TGFBI." (PMID 19461933, 2009). "In Japanese individuals, ACD is the most common hereditary corneal dystrophy, responsible for 72% of corneal dystrophies associated with TGFBI." (PMID 19145249, 2009). "As far as we are aware, this is the first report of a patient with a double mutation of TGFBI causing an autosomal dominant form of corneal dystrophy." (PMID 19461933, 2009). "The genetic studies revealed specific missense mutations in TGFBI, causing diverse hereditary corneal dystrophies." (PMID 19956413, 2009). "A few case reports have also described individuals with corneal dystrophy who harbor two distinct mutations in TGFBI, the membrane component, chromosome 1, surface maker 1 (M1S1), or both." (PMID 19461933, 2009). "So far, all the pathogenic mutations reported on TGFBI are only related to corneal dystrophies, which are characterized by progressive accumulation of deposits in the cornea." (PMID 19956413, 2009). "Genetic analyses have linked several mutations of the TGFBI gene to various corneal dystrophies, including Avellino, lattice dystrophies, Reis-Bucklers dystrophies, and granular dystrophies." (PMID 20011632, 2009). "All the mutations of TGFBI that cause corneal dystrophy are located in FAS1 domain 4, with the exception of Arg124." (PMID 19956413, 2009). "ACD (also known as GCD-II) is one of the TGFBI associated corneal dystrophies, of which the clinical aspect is the coexistence of granular deposits and histological amyloidal deposits in the cornea." (PMID 19145249, 2009). "As far as we are aware, this is the first report of a patient with a double mutation (R124H, N544S) of TGFBI causing an autosomal dominant form of corneal dystrophy." (PMID 19461933, 2009). "The novel gene mutation expands the mutation spectrum of TGFBI and contributes to the study of molecular pathogenesis of corneal dystrophy." (PMID 19956413, 2009). "Immunohistological studies have shown TGFBIp to be present in the abnormal corneal deposits seen in certain corneal dystrophies, as well as in secondary amyloidosis in corneal disease unrelated to TGFBI mutations." (PMID 18728790, 2008). "Molecular genetic studies of 5q31-linked corneal dystrophies have demonstrated a clear genotype-phenotype correlation as specific TGFBI gene mutations cause defined forms of CD." (PMID 18615206, 2008). "Corneal dystrophy of Bowman’s layer (CDB) belongs to a group of dystrophies associated with mutations in the transforming growth factor-beta-induced (TGFBI) gene." (PMID 18728790, 2008).
corneal dystrophies (continued). "We hypothesized that the accumulation of the pathogenic mutant‐TGFBIp in the corneal fibroblasts may be caused by lysosomal abnormalities and that the enhancement of lysosomal function might counteract the progression of TGFBI‐linked corneal dystrophies." (PMID 32667742, 2020). "Corneal deposits in TGFBI corneal dystrophy may be caused by abnormal accumulation of TGFBIp resulting from mutated TGFBI4." (PMID 32029872, 2020). "These surface corneal surgeries induce a wound in the stromal layer, which causes the expression of TGFBI to be upregulated, resulting in corneal amyloid deposition within the corneas of individuals who carry the TGFBI mutations leading to pathology associated with corneal dystrophy." (PMID 30760895, 2019). "Through clinical investigation and molecular genetic analysis, the present study has identified three Chinese families with corneal dystrophies caused by R124 mutations in the TGFBI gene and has demonstrated, once again, that R124 is a mutational hotspot in TGFBI-related corneal dystrophies." (PMID 30805211, 2019). "Overall, 57 mutations in the TGFBI gene have been associated with corneal dystrophies." (PMID 30753226, 2019). "Ultimately, gene therapy with tools such as CRISPR/Cas9 system may provide an effective treatment strategy to repair the gene sequences mutated in TGFBI-related corneal dystrophies." (PMID 30753226, 2019). "Future, we need more samples to reveal the TGFBI gene mutation with corneal dystrophy." (PMID 30805211, 2019). "Because corneal dystrophy is commonly caused by dominant mutations in the TGFBI gene, we hypothesize that this disease is suited for gene therapy with genome-editing technology." (PMID 30753226, 2019). "Corneal dystrophy is commonly caused by dominant mutations in the TGFBI gene, and thus, we hypothesize that this is a disease ideally suited for gene therapy with genome editing technology." (PMID 30753226, 2019). "Therefore, interaction between TGFBIp and collagen is important for understanding the pathobiology of TGFBI-linked corneal dystrophies." (PMID 30753226, 2019). "Therefore, it is difficult to classify and type TGFBI-associated corneal dystrophies simply based on their clinical features or histological manifestations." (PMID 30805211, 2019). "Rare variants in the ZNF469 gene (mutated in corneal dystrophy Brittle Cornea Syndrome) and in the TGFBI gene (mutated in multiple corneal epithelial–stromal TGFBI dystrophies) have been repeatedly identified in familial and sporadic KC patients of different ethnicities." (PMID 27350955, 2016). "The gene TGFBI encodes for the transforming growth factor beta-induced protein, which contributes to cell-collagen interaction and has been linked to protein aggregates in individuals with corneal dystrophy." (PMID 26807844, 2016). "Taken together, these results support the hypothesis that impaired TGFBIp endocytosis resulting from an age-dependent decrease in the ubiquitin-proteasome system leads to age-dependent accumulation and deposition of TGFBIp in TGFBI-linked corneal dystrophy." (PMID 25853243, 2015). "Therefore, degradation of mutant TGFBIp via internalization before or/and after deposition in the ECM is a potentially effective strategy for targeted drug intervention in TGFBI-linked corneal dystrophy." (PMID 25853243, 2015). "Such knowledge might lead to the identification of novel targets and the development of new therapies for the treatment of TGFBI-linked corneal dystrophy." (PMID 25853243, 2015). "These insights on TGFBIp trafficking could lead to the identification of novel targets and the development of new therapies for TGFBI-linked corneal dystrophy." (PMID 25853243, 2015). "Furthermore, several studies have shown that proteolytic processing of mutant TGFBIp is involved in the pathogenesis of TGFBI-linked corneal dystrophy." (PMID 25853243, 2015).
corneal dystrophies (continued). "Spectrum of clinical changes in corneal dystrophy associated with TGFBI gene may show an accumulation of deposits in the epithelium, Bowman’s layer and stroma regardless of the type of point mutations." (PMID 23837658, 2013). "Although spontaneous mutations are therefore implicated in 12% (3/25) of probands with PPCD with ZEB1 mutations, these mutations have been identified in only one other gene associated with a corneal dystrophy, the transforming growth factor, beta-induced (TGFBI) gene." (PMID 23559851, 2013). "Corneal dystrophy phenotypes and mutation analysis in TGFBI (5q31)." (PMID 22876129, 2012). "Further large-scale studies involving more Taiwanese families with TGFBI-linked corneal dystrophies are required to confirm our preliminary findings and the speculation of the relationship between Taiwanese and other Asian population." (PMID 22355247, 2012). "We show that both Leu509 variants of TGFBI cause corneal dystrophy of the lattice type." (PMID 21617751, 2011). "Now, while the insight offered by these findings remains valuable, the genotype-phenotype correlation of these corneal dystrophies has gradually gained in complexity; it has been well demonstrated that some TGFBI mutations have shown significant phenotypic variability." (PMID 21617751, 2011). "Most of the TGFBI mutations associated with corneal dystrophies are heterozygous." (PMID 20664689, 2010). "Mutated TGFBI has been linked to the four types of corneal dystrophy, including RBCD." (PMID 20360992, 2010). "Mutations of the keratoepithelin gene (TGFBI) are responsible for most corneal dystrophies." (PMID 19461933, 2009). "The penetrance of corneal dystrophies caused by the R124H or N544S mutations of TGFBI remains unclear." (PMID 19461933, 2009). "When both parents have GCD their offspring may be homozygous for the TGFBI mutation and develop an unusually severe corneal dystrophy with larger corneal opacities and an earlier onset than heterozygous cases." (PMID 19236704, 2009). "This is the only amino acid residue where numerous mutations are reported, suggesting this may be a “hot spot”, as is observed with the 124 and 555 arginine in TGFBI - associated corneal dystrophies." (PMID 19997581, 2009). "Non-penetrance may also be an issue as has been described occurring in fleck dystrophy associated with PIP5K3 mutations and in some of the TGFBI – associated corneal dystrophies." (PMID 19710953, 2009). "Currently, more than 30 missense mutations of TGFBI have been identified and linked to at least 13 different phenotypes of corneal dystrophies, characterized by the presence of abnormal amyloid fibril and/or non-amyloid deposits in sub-epithelial and stromal layers in the cornea." (PMID 20011632, 2009). "Defects in TGFBI are the cause of several types of corneal dystrophies." (PMID 18298822, 2008). "Heterozygous mutations in TGFBI have typically caused corneal dystrophies." (PMID 18385782, 2008). "Thus far, the R124L mutation in TGFBI is the only one found to be associated with this type of corneal dystrophy in Chinese patients." (PMID 18636123, 2008). "This study and recent molecular evidence therefore highlights the ongoing complexity of the pathogenesis of TGFBI associated corneal dystrophies, and emphasizes the need to review the current nomenclature used to define TGFBI-associated dystrophies of Bowman’s layer." (PMID 18728790, 2008). "Nevertheless, further studies are needed in the future to determine whether mitochondrial abnormalities directly result from mutant-TGFBIp, and to define more precisely the role of mitochondrial quality control including mitophagy in the pathophysiology of TGFBI-linked corneal dystrophy." (PMID 36980838, 2023). "Thus, compound heterozygosity of TGFBI is associated with the phenotypic variability of TGFBI corneal dystrophies, suggesting that identifying TGFBI second mutations may be vital in patients with extraordinarily severe phenotypes." (PMID 33772078, 2021).
corneal dystrophies (continued). "Thus, targeting the proteolytic machinery involved in TGFBIp processing may provide a way to prevent or delay the disease progression of TGFBI-linked corneal dystrophy." (PMID 31197037, 2019). "Moreover, atypical variants of TGFBI-associated corneal dystrophy are frequently reported." (PMID 30805211, 2019). "Therefore, we postulate that the ~66 kDa form of TGFBIp might be important in the progression of TGFBI-linked corneal dystrophy and might facilitate the physiological process related to ECM remodeling, wound healing, development, and cancer." (PMID 25853243, 2015). "Hence, screening for mutations in TGFBI may facilitate the classification of corneal dystrophies, especially in the cases of atypical clinical presentations." (PMID 22355247, 2012). "The role of TGFBI in the pathogenesis of the chromosome 5q31-linked corneal dystrophies still remain unclear, but TGFBIp is preferentially expressed on the extracellular surface of corneal epithelial cells and pathologic deposits caused by TGFBIp accumulation were only observed in the cornea." (PMID 21311742, 2011). "How mutations of TGFBI cause corneal dystrophy is still unknown." (PMID 22194646, 2011). "This case exemplifies the critical importance of recognizing TGFBI-related corneal dystrophies as absolute contraindications to laser refractive surgery." (PMID 41446838, 2025). "We hope this report will provide valuable insight into the phenotype–genotype correlation of TGFBI-related corneal dystrophies." (PMID 39858623, 2025). "In 1997, a group at the University of Lausanne reported TGFBI gene abnormalities in corneal dystrophy (OMIM 601692)." (PMID 39271608, 2024). "In case nm1 with AD lattice dystrophy caused by TGFBI, the accumulation of transforming growth factor beta-induced protein (TGFBIp) is involved in the pathogenesis of TGFBI corneal dystrophies." (PMID 38785568, 2024). "Transforming growth factor beta-induced (TGFBI) corneal dystrophy is a bilateral corneal disease characterized by an abnormal deposition of extracellular matrix." (PMID 35962009, 2022). "There are abundant reports of exacerbation of TGFBI-related corneal dystrophies, including GCD2 or GCD1 with deposits, following corneal trauma such as laser-assisted in situ keratomileusis, LASEK, photorefractive keratectomy, and refractive keratotomy." (PMID 33772078, 2021). "In conclusion, we have shown the distribution of genotype and phenotype of TGFBI corneal dystrophies in a multi-ethnic population in Singapore." (PMID 33513810, 2021). "Further studies with larger patient group are needed for evaluation of the influence of ethnicities on expressivity of TGFBI corneal dystrophies." (PMID 33513810, 2021). "Regarding the phenotypes of TGFBI corneal dystrophy, the subjects comprised 11 (34.4%) patients with GCD1, 6 (18.8%) patients with GCD2, 13 (40.6%) patients with LCD, 2 (6.3%) patients with RBCD." (PMID 33513810, 2021). "Although TGFBI corneal dystrophies are autosomal dominant hereditary disorders, R124H heterozytes have been shown to tend to show less severe corneal opacity than homozygotes." (PMID 33513810, 2021). "In general, the results of this study indicated moderate genotype/phenotype correlation in TGFBI corneal dystrophies, such as, R555W and GCD1, R124H and GCD2, and R124C and LCD, which corroborate with previous studies." (PMID 33513810, 2021). "The differences in phenotypes and genotypes among different ethnicities in Singapore in the present study suggest that the frequency of TGFBI corneal dystrophies can vary among different races, although this study included relatively small number of patients." (PMID 33513810, 2021). "Nonetheless, our findings reveal that the corneal opacity was caused by the accumulation of mutant TGFBIp, similar to that observed in TGFBI corneal dystrophy in humans." (PMID 32029872, 2020).
corneal dystrophies (continued). "Because we did not use artificial overexpression of mutant genes to establish our mouse model of TGFBI corneal dystrophy, our mice likely required more time to form amyloid plaques." (PMID 32029872, 2020). "In conclusion, our novel mouse model of TGFBI-R124C corneal dystrophy reproduces features of the human disease." (PMID 32029872, 2020). "Consistent with the patterns observed in human corneal dystrophy, we detected a well-defined mass in the central cornea of the TGFBI-R124C mice." (PMID 32029872, 2020). "Although mutations in genes such as KRT3, KRT12, PIP5K3, TGFBI, and UBIAD1 have been associated with specific corneal dystrophies, genes associated with all corneal dystrophies have yet to be identified." (PMID 32823625, 2020). "Among these, transforming growth factor-beta-induced (TGFBI) corneal dystrophies occur most frequently in East Asian populations." (PMID 32029872, 2020). "We targeted the arginine residue at position 124 of TGFBI; this amino-acid residue is important in the development of TGFBI corneal dystrophy." (PMID 32029872, 2020). "Characterising corneal dystrophy via our TGFBI-R124C mouse model will help to uncover the mechanisms driving the pathogenesis of human TGFBI corneal dystrophies." (PMID 32029872, 2020). "LCDs and GCDs are transforming growth factor beta induced protein (TGFBI)-linked corneal dystrophies and heterozygous mutations in TGFBI (OMIM 601692, previously called BIGH3), on human chromosome 5q31 is responsible for the disease." (PMID 32952948, 2020). "Two animal models of TGFBI corneal dystrophy have been established via introduction of human mutant TGFBI genes into mice." (PMID 32029872, 2020). "Over the years, our understanding of the pathogenesis of TGFBI-related corneal dystrophies has advanced significantly, but much remains to be learned." (PMID 30753226, 2019). "In brief, the study consisted of 91 unrelated TGFBI corneal dystrophy cases in which 68 had a diagnosis of epithelial-stromal TGFBI associated dystrophy (RBCD, TBCD, LCD, and GCD) and 23 had a diagnosis of bilateral EBMD." (PMID 30760895, 2019). "In this study, we reviewed reports in the literature on various TGFBI corneal dystrophies to understand the prevalence of this disease." (PMID 30760895, 2019). "After uncovering of association between different mutations of TGFBI gene with significant phenotypes of corneal dystrophies, it is feasible to explore the outcome of PTK treating corneal dystrophies with different TGFBI gene types." (PMID 31438893, 2019). "Most reports describe the role of TGFBI in corneal dystrophy and in promoting glioma cell proliferation and migration." (PMID 31485443, 2019). "Dysregulation of TGFBI has been observed not only in cancers but also in corneal dystrophy and diabetes." (PMID 28106769, 2017). "Given the lack of effective treatment options for GCD2, this gene editing system is a potentially radical treatment for TGFBI-related corneal dystrophy and can be used to protect corneal opacities." (PMID 29196743, 2017). "The TGFBI protein has been identified in primary amyloid deposits of hereditary corneal dystrophies and in secondary corneal amyloidosis of diverse etiologies as well as in corneal stromal amyloid deposits in KC patients." (PMID 27350955, 2016). "Further genetic analysis of TGFBI in cases in which corneal dystrophy is suspected can help identify patients with atypical GCD2 and prevent this adverse event from occurring after LASIK surgery." (PMID 22355247, 2012). "It is therefore necessary to investigate the effect of mutant TGFBIp on cell ER stress, thereby shedding light on the pathogenesis of TGFBI-related corneal dystrophies." (PMID 22605926, 2012). "In this paper, we present the results of a clinical and genetic analysis of a Korean population of patients with TGFBI-related corneal dystrophies." (PMID 22876129, 2012).